MET (MET proto-oncogene, receptor tyrosine kinase)
Diseases named in the same sentence as MET in open-access papers (continued):
Sharing a sentence is not in itself a finding about the gene and the disease.
breast carcinoma (continued). "In previous studies, CCR2 and MET co-expression correlated with the invasiveness of breast cancer cells." (PMID 40736024, 2025). "Although MET fusions are well-documented oncogenic drivers in malignancies such as renal cell carcinoma, non-small cell lung cancer, colorectal cancer, and breast cancer, their role in thyroid carcinogenesis remains poorly characterized." (PMID 40636652, 2025). "The hepatocyte growth factor (HGF)/MET signaling pathway is also involved in the regulation of breast cancer by CAFs." (PMID 40890855, 2025). "In preclinical and clinical studies, the HGF/c-MET signaling pathway has been found to play a significant role in breast cancer tumorigenesis and disease progression, contributing to the invasive phenotype seen in many tumors." (PMID 40361420, 2025). "MET is another receptor tyrosine kinase that plays a role in breast cancer cell growth, invasion and angiogenesis." (PMID 40560045, 2025). "Among them, the HGF/c-MET pathway is closely related to cancer metastasis and can promote breast cancer resistance to tamoxifen through the EZH2/HOTAIR-MIR-141/200A feedback signaling pathway." (PMID 40860340, 2025). "Across all types of breast cancers, at least 20–30% of cases show c-MET overexpression, and HGF and c-MET are often co-expressed in invasive breast cancers." (PMID 40361420, 2025). "Reactive oxygen species (ROS), particularly H2O2, can also induce retrograde trafficking of full-length c-MET from the plasma membrane to the nucleus in breast cancer cells." (PMID 40361420, 2025). "The HGF (hepatocyte growth factor)/MET pathway plays an important role in normal mammary development and various breast cancer progression processes, including migration, invasion, and tubulogenesis." (PMID 40560045, 2025). "Among these, antibodies 87B156 and 69B287 effectively bound to tumor cells and inhibited MET-expressing breast cancer cell lines." (PMID 40401526, 2025). "This kinome reprogramming involved RTKs including FGFR2, ERBB2 and MET that were heterogeneously upregulated in different HER2+ breast cancer cell lines growing in the presence of lapatinib." (PMID 39513002, 2024). "This study investigated the expression of MET, ESR1, and ESR2 genes and their association with clinicopathologic characteristics and clinical outcomes in patients with breast cancer." (PMID 39742369, 2024). "Mast cells have been shown to induce the expression and activation of ESR1 and its target genes promoting luminal phenotype while concomitantly suppressing the activation of MET in breast cancer using in vivo and in silico models." (PMID 39742369, 2024). "The MET expression correlated with poor prognosis in several studies in patients with breast cancer." (PMID 39742369, 2024). "In breast carcinoma cells, the Sema4D activation of Plexin B1 leads to its tyrosine phosphorylation by MET, creating a docking site for the SH2 domain of Grb2." (PMID 39769452, 2024). "In breast cancer, recent findings also indicate that the loss of PTPN12 phosphatase function activates several oncogenic RTKs such as MET, PDGFRb, HER2, and EGFR, positioning PTPN12 as a master regulator of protein tyrosine kinases." (PMID 38612874, 2024). "MET signalling has been identified to drive cancer recurrence as an evasion strategy to HER2 antibodies in breast cancer." (PMID 38891113, 2024). "Previous studies have investigated the coexpression of MET and other target receptors in breast cancer and their impact on disease presentation and prognosis." (PMID 39742369, 2024). "Further evidence showed that pharmacologic inhibition of MET reversed resistance of the endocrine drugs in breast cancer cell lines." (PMID 39742369, 2024). "In breast cancer, MET overexpression is detected in 20%–30% of all cases and 52% of triple-negative tumors." (PMID 39742369, 2024). "A specific role for the MET/β1 integrin complex has been identified in breast cancer cell intravasation, showing a preferential affinity for bone type 1 collagen." (PMID 39769452, 2024).
breast carcinoma (continued). "Although the individual roles of ERs and MET in breast cancer have been illustrated, there remains limited knowledge regarding their coexpression and the resultant impact on the clinicopathologic features and prognosis of the disease." (PMID 39742369, 2024). "High expression levels of both EGFR and c-MET in a TCGA data cohort significantly correlate with unfavorable overall survival in breast cancer patients." (PMID 37924112, 2023). "Pathogenic variants in the FANCI, MET and STK11 have been reported in association with breast cancer." (PMID 37277882, 2023). "In parallel, it was shown in various cancers including breast cancer that MET targeting acts synergistically with RT as these approaches target different tumor niches." (PMID 37173782, 2023). "Distribution of VUS in breast cancer predisposing genes were :APC:1(5.8%), ATM:2(11.7%), BRCA1:1(5.8%), BRCA2:5(29.4%), BRIP1:1(5.8%), CDKN2A:1(5.8%), CHEK2:2(11.7%), FANC1:1(5.8%), MET:1(5.8%), STK11:1(5.8%), NF2:1(5.8%)." (PMID 37277882, 2023). "High levels of MET correlate with poor prognosis in breast cancer, and therapeutic targeting of cMET has been of interest in breast, melanoma, and other cancers." (PMID 37377890, 2023). "For example, in MB-231 breast cancer cells grown in culture and in vivo, FM-miR-34a induced stronger silencing of MET and CD44 in comparison to PM-miR-34a." (PMID 37666938, 2023). "In immunoblot analysis of a panel of breast cancer cell lines, we observed that the protein content and phosphorylation status of c-MET were relatively higher in TNBC when compared to luminal or HER2-positive subtypes." (PMID 37924112, 2023). "According to the TCGA database, c-MET mRNA expression levels in TNBC patients are higher than in other subtypes of breast cancer (p<0.01)." (PMID 37924112, 2023). "Here, we highlight that MET protein physically interacts with glutamate receptors in two highly metastatic breast cancer cell lines." (PMID 36139568, 2022). "Levels of THEMIS2 and p-MET protein were significantly correlated in the 465 breast cancer specimens." (PMID 34974522, 2022). "Another interesting study suggested that the HGF/MET signaling pathway in CAFs was activated, and secreted HGF conferred gefitinib resistance in breast cancer by increasing MET phosphorylation." (PMID 36359776, 2022). "In a study of 130 patients with HER-2-positive breast cancer, both MET and HGF amplification were associated with trastuzumab failure and patients with MET amplified tumors had a shorter time to progression." (PMID 35069735, 2022). "Expression levels of THEMIS2 and p-MET protein were positively correlated in the 465 breast cancer specimens." (PMID 34974522, 2022). "Many studies have looked at the HER family, mesothelin (Meso), folate receptor alpha (FR‐α), NKG2D ligands, c‐MET, and mucin 1 (Muc1) as potential targets for breast cancer in vitro and in animal models that will be discussed in the following sections." (PMID 35762299, 2022). "CRISPR knockout and pharmacologic inhibition of MET revealed that CCL2/CCR2-induced breast cancer cell proliferation, survival, migration and glycolysis through MET-dependent mechanisms." (PMID 35405500, 2022). "Its receptor, c-MET, is expressed at high levels in breast cancer cells situated at the interface with adipocytes, highlighting the importance of stromal–tumor cell interactions in mammary tumor growth." (PMID 36077676, 2022). "By screening different breast cancer cell lines, we found that triple-negative breast cancers co-express high levels of MET and NMDAR2B." (PMID 36139568, 2022). "MET CNA has been reported to be associated with resistance to anti-HER2 TKIs in EGFR-mutant NSCLC, HER2-amplified breast cancer, and HER2-mutated NSCLC." (PMID 35101045, 2022). "MET is a receptor tyrosine kinase, deregulated in many types of human malignancies including breast cancer, lung cancer, bladder cancer, hepatocellular carcinoma, and melanoma." (PMID 33596979, 2021).
breast carcinoma (continued). "HER2-positive basal-like breast cancers can activate MET with expression of its ligand, the hepatocyte growth factor (HGF), particularly in liver where HGF is high." (PMID 33772089, 2021). "Crizotinib, a small-molecule tyrosine kinase inhibitor of MET, exhibited a significant anti-tumor effect in breast cancer cells when combined with endocrine drugs." (PMID 34804015, 2021). "Previous studies have shown that HGF and MET expression are elevated and correlated with progression and poorer prognosis in breast cancer patients." (PMID 34381422, 2021). "hsa-miR-27b-3p directly targets HSP90AA1 and Fzd7 in NSCLC, ROR1 in gastric cancer, and CBLB/GRB2 in breast cancer to suppresses cell proliferation, migration, invasion, and expression of MET." (PMID 34603447, 2021). "In this murine model of basal breast cancer, the endogenous MET locus becomes amplified and Met kinase activity is required to sustain both the EMT phenotype and proliferation of spindloid tumour cells." (PMID 33772015, 2021). "The HGF/c-MET axis is an attractive pathway in breast cancer research because it is targetable with existing therapeutics." (PMID 34344422, 2021). "HGF/MET signaling disrupted TJs in the breast cancer cell lines MDA-MB-231 and MCF-7 by downregulating the expression of several important TJ molecules, such as occludin, at both transcript and protein levels." (PMID 33917539, 2021). "For example, in MCF-7 breast cancer cells and other cell types, E-cadherin associates with MET and this interaction increased after HGF treatment leading to HGF-MET signaling amplification." (PMID 32823931, 2020). "Remarkably, the prognostic value of HGF and c-MET is contradictory to the findings in female breast cancer." (PMID 32188473, 2020). "OLE is a unique tyrosine-protein kinase Met (c-MET) inhibitor for the control of breast cancer progression and loco regional recurrence." (PMID 32050687, 2020). "Nuclear YBX1 has been reported to promote MET expression by directly binding to the MET promoter in basal-like breast cancers." (PMID 33312753, 2020). "Tumors that recurred after PIK3CA inactivation acquired focal amplification of MET or MYC in an in vivo mouse breast cancer model expressing PIK3CAH1047R34." (PMID 32409685, 2020). "Except with IL-10, treatment with MET has shown marked differences between its action when MOs are cultured alone and when co-cultured with breast cancer cells." (PMID 33108409, 2020). "A breast cancer cell line (BT-20) and cervical cancer cells (HeLa) were selected due to distinctly different MET:EGFR expression levels." (PMID 32316583, 2020). "MET treatment significantly downregulated breast cancer cell proliferation and viability levels (for both comparisons, p < 0.05)." (PMID 33108409, 2020). "Another investigated drug, Tivantinib, has also shown positive effect on breast cancer model by reducing the metastasis via c-MET inhibition." (PMID 32503412, 2020). "BMS-777607 is currently undergoing phase II clinical trials for a number of different cancers, including breast cancer, and has activity against MET (IC50 3.9 nM), MERTK (IC50 14 nM) and NTRK1 (IC50 290 nM)." (PMID 30898150, 2019). "Surprisingly, MCF7 breast cancer cells survived upon treatment with Dox, but Dox became effective when cells were treated with the antibody against MET." (PMID 30700325, 2019). "Cabozantinib is also undergoing phase II clinical trials for breast cancer and has activity against MET (IC50 1.3 nM) and TIE-2 (IC50 14.3 nM)." (PMID 30898150, 2019). "Administration of this inhibitor induced MET by reversal of E‐ to N‐cadherin switching in breast cancer cell lines expressing high levels of FOXC2, and reduced CSC properties and metastatic capabilities." (PMID 31464093, 2019).
breast carcinoma (continued). "In contrast, the MET gene shows a lower expression level in group 1 of breast cancer samples than in group 2 of breast cancer samples or normal samples." (PMID 31856825, 2019). "As expected, many established oncogenes in distinct malignancies were detected including ERBB2 in breast cancer, MET in stomach tumor and BCL2 in leukemia/lymphoma." (PMID 31050342, 2019). "Positive correlation of MET with TGFBR2 gene expression was also observed in breast cancer tissue using the breast cancer TCGA dataset and, at the protein level, in 801 breast cancer specimens." (PMID 30004628, 2018). "A crosstalk mediated by HGF/c-MET between ASCs and breast cancer cells increased the invasion ability of cancer cells and their growth rate." (PMID 30335754, 2018). "As expected, surface protein levels of MET were reduced in MCF10A as well as in all tested basal‐like breast cancer cell lines HS578T, MDA‐MB‐468, MDA‐MB‐231, BT549, and HCC1143 upon overexpression of miR‐128‐3p." (PMID 30004628, 2018). "In a study conducted by Ho-Yen, it was found that MET signaling was directly related to breast cancer progression, and anti-MET treatment proved effective for basal-like type 5 and TNBC type 6 breast cancers." (PMID 30386383, 2018). "In this study, we performed genomewide correlation analysis of TGFBR2 expression in a panel of 51 breast cancer cell lines and identified that MET is coregulated with TGFBR2." (PMID 30004628, 2018). "In fact, AXL and MET are known oncogenes, and different studies show that they have roles in progression of breast cancer." (PMID 30386383, 2018). "Treatments using anti-MET agents are effective in basal-like breast cancer and triple-negative breast cancer (TNBC)." (PMID 30386383, 2018). "Ho-Yen and colleagues showed that MET signaling has a direct role in the development and progression of breast cancer." (PMID 30386383, 2018). "Next, we tested the impact of miR‐128‐3p on MET expression in MET‐positive breast cancer cell lines." (PMID 30004628, 2018). "In contrast, MET was expressed at substantial levels in basal‐like breast cancer cell lines MDA‐MB‐468, BT549, HS578T, MDA‐MB‐231, and HCC1143, as well as the HER2‐enriched cell line HCC1954 and in the immortalized breast epithelial cell line MCF10A." (PMID 30004628, 2018). "C‐ets‐1 was the top candidate as this transcription factor has previously been described to synergize with SMAD3 and its expression also correlated the most with expression of TGFBR2 as well as of MET in breast cancer cell lines." (PMID 30004628, 2018). "Co-expression of CD44v6 and MET was observed to be particularly important for metastasis initiation where interaction with HGF in breast cancer metastases enhanced MET-kinase signaling." (PMID 29710776, 2018). "Flow cytometry examination in U87-MG (human glioblastoma) and MDA-MB-231(human breast cancer) cell lines, which have moderate level and low level expression of c-MET, respectively, confirmed the specific binding capacity of rh-HGF to c-MET." (PMID 28485003, 2017). "The AH113804 peptide has also been labelled with 18F for PET, and is able to detect recurrence of c-MET-expressing basal-like breast cancer xenografts after surgical resection." (PMID 28315949, 2017). "Multiple studies have demonstrated a strong relationship between HGF/MET signaling and breast cancer progression." (PMID 27055285, 2016). "In HER2-overexpressing breast cancer cells, MET aberrations also contribute to trastuzumab resistance." (PMID 27055285, 2016). "Most recently, EpCAM, CD44 and MET have also been identified in circulating tumor cells (CTCs) of breast cancer patients exhibiting metastasis." (PMID 26243458, 2016). "For example, HGF signaling through its receptor (MET) facilitated resistance to lapatinib in HER2 amplified breast cancer cells via activation of PI3K and MAPK." (PMID 27608848, 2016).
breast carcinoma (continued). "These variable patterns of membrane and cytoplasmic MET expression have been observed in other breast cancer studies, yet the consequences of membrane vs. cytoplasmic expression on MET signaling and clinical outcome is unclear." (PMID 27655711, 2016). "Overexpression and increased gene copy numbers of HGF and MET in tumor tissues were associated with the resistance to and failure of trastuzumab treatment in HER2-postive breast cancer." (PMID 26716644, 2016). "c-MET has been found to be highly expressed in prostate cancer bone lesions, and a c-MET inhibitor reduced bone metastasis progression in breast cancer." (PMID 27322553, 2016). "Overexpression of c-MET in tumour tissue has been noted in many cancers, such as lung cancer, stomach cancer, breast cancer, kidney cancer, colon cancer, and HCC." (PMID 28943627, 2015). "Mice harboring an activating mutant MET knock-in or mutant MET transgene under mouse mammary tumor virus promoter, develop breast cancers with a triple-negative phenotype." (PMID 26123926, 2015). "High protein levels of MET and p-MET were found in 257 patients and correlated with poor prognosis for PFS and OS in HER2-positive breast cancers and associated with a significantly higher risk of recurrence and death (p < 0.05)." (PMID 28536405, 2015). "A crosstalk between human adipose-derived mesenchymal stem cells (ADSCs) and breast cancer cells mediated by HGF/c-MET signaling has been reported to enhance tumor cells migration, acquiring a metastatic signature, and sustained tumor self-renewal." (PMID 28536400, 2015). "Other mutations within c-MET’s juxtamembrane region or its Sema domain, where HGF binds, have also been noted in gastric cancer, breast cancer, pleural mesothelioma, and small-cell lung cancer." (PMID 28943627, 2015). "STAT3 was activated by IL-6 in myeloma and prostate cancer cells, hepatocyte growth factor (HGF) and its receptor (c-MET) in leiomyosarcoma and breast cancer cells, and Src in breast cancer and melanoma cells." (PMID 24675568, 2014). "This is consistent with high expression and amplification of the MET gene in human basal breast cancers and amplification of the Met/Cav1 locus in basal-like mammary tumours in mice with mammary-specific deletion of Lfng." (PMID 25200860, 2014). "We have previously shown the involvement of the HGF/MET system in tumor-bone interaction contributing to human breast cancer metastasis." (PMID 24260160, 2013). "Our results emphasize that HGF/MET signaling is important in basal-like breast cancer progression from early in the disease, but HGF has long been studied in invasive cancer biology and in normal development." (PMID 24025166, 2013). "In a previous work, our group has demonstrated the effectiveness of MET inhibition, by both tivantinib (ARQ 197) and a specific short hairpin RNA (shRNA) against MET, in delaying the onset of experimental breast cancer-derived bone metastases." (PMID 24260160, 2013). "We have also reported the effectiveness of MET inhibition, by both a MET inhibitor, tivantinib, and a specific short hairpin RNA (shRNA) against MET, in a mouse model of human breast cancer, in delaying the onset and progression of bone metastases." (PMID 24260160, 2013). "We found that expression of IGF1-R was present in 38.5%, FGFR2 in 12.1%, EGFR in 11.4%, HER2 in 3.0%, and MET in 4.5% of male breast cancers." (PMID 23308200, 2013). "Our data, using a novel HGF signature and three independent tumor datasets, indicate that HGF/MET signaling is highly correlated with basal-like breast cancer subtype and worse overall survival in patients." (PMID 24025166, 2013). "Several lines of evidence have demonstrated that MET inhibits the growth of tumor cells, including breast cancer cells." (PMID 26097796, 2012). "MET expressing breast cancer cell population display cancer stem cell characteristics, and studies illustrated that c-MET is closely related with highly aggressive cancer cell type." (PMID 22253909, 2012).